NINJ2 (ninjurin 2)
Description:
Its role in unclear. In contrast to NINJ1 paralog, does not mediate plasma membrane rupture (cytolysis) downstream of necroptotic and pyroptotic programmed cell death. While it is able to oligomerize and form filaments, filaments are curved toward the intracellular space, preventing circularization to mediate plasma membrane rupture. May act as a homophilic transmembrane adhesion molecule involved in nerve regeneration. Promotes axonal growth.
Tractability: Small molecule: a structure with a bound ligand is known. Antibody: UniProt places it where antibodies can reach, with high confidence; its Gene Ontology location is reachable by antibodies, with high confidence; UniProt predicts a signal peptide or a membrane-spanning region; the Human Protein Atlas places it where antibodies can reach.
Gene: Protein-coding gene on chromosome 12 (562,852 to 663,742, reverse strand). Ensembl gene ENSG00000171840.
Subcellular location: Cell membrane
Subcellular location (Human Protein Atlas): Endoplasmic reticulum; Plasma membrane
Gene Ontology:
Molecular function: cholesterol binding; membrane destabilizing activity; protein binding; cell-cell adhesion mediator activity
Biological process: cytolysis; cell adhesion; nervous system development; neuron cell-cell adhesion; tissue regeneration
Cellular component: plasma membrane; membrane
Genetic constraint (gnomAD): Loss-of-function variants: 12 observed, 12.42 expected, observed/expected ratio (o/e) 0.97, 90% interval 0.62 to 1.55. The upper end of that interval is the gene's LOEUF score, 1.55, which puts it in group 6 of 6, group 1 being the genes least tolerant of losing a copy. Missense variants: 187 observed, 191.64 expected, observed/expected ratio (o/e) 0.98, 90% interval 0.87 to 1.1. Synonymous variants: 93 observed, 80.83 expected, observed/expected ratio (o/e) 1.15, 90% interval 0.97 to 1.37.
Homologues: Orthologues: chimpanzee NINJ2 (99% identical), macaque NINJ2 (94% identical), dog NINJ2 (89% identical), guinea pig NINJ2 (79% identical), rat Ninj2 (78% identical), mouse Ninj2 (73% identical), tropical clawed frog ninj2 (60% identical), zebrafish ninj2 (52% identical), Drosophila melanogaster NijC (32% identical). Paralogues in human: NINJ1 (53% identical).
Diseases named in the same sentence as NINJ2 in open-access papers:
NINJ2 is named in the same sentence as 50 diseases in open-access papers, as found by Europe PMC text mining. Sharing a sentence is not in itself a finding about the gene and the disease. The quoted sentences say what the papers report.
Stroke (12 papers, 2011 to 2026). Sudden impairment of blood flow to a part of the brain due to occlusion or rupture of an artery to the brain. "This study identified two SNPs (rs11833579 and rs12425791) in the 12p13 region of chromosome 12 and within 11 kb upstream of the gene NINJ2 (Ninjurin 2), all of which were significantly associated with stroke." (PMID 35326259, 2022). "In particular, cumulative burden of rare alleles that affect NINJ2 gene regulation or function was associated with a lower stroke incidence." (PMID 24959832, 2014). "The aim of present study was to investigate the relationship between nerve injury-induced protein 2 (NINJ2) gene polymorphism and stroke in Chinese Han population." (PMID 23554703, 2011). "Mutations in the NINJ2 gene have been linked to an increased risk of stroke and multiple sclerosis." (PMID 40567024, 2025). "Moreover, the researchers also found the SNP rs12425791 of NINJ2 was significantly associated with ischemic stroke, and A allele increases the susceptibility of stroke." (PMID 33397383, 2021). "These evidence support the hypothesis of our study that the minor allele of NINJ2 gene might be related to greater stroke severity." (PMID 22212150, 2012). "NINJ2 plays a role in nerve regeneration and may increase the risk of stroke by altering brain response to ischemic injury." (PMID 22212150, 2012). "We additionally tested whether SNPs from NINJ2, which was identified in a prior large GWAS study to be associated with IS, were associated with young-onset stroke in our study." (PMID 22384361, 2011). "Thus, variants that affect NINJ2 regulation or function may influence stroke risk, either favorably or unfavorably." (PMID 24959832, 2014). "Concerning to study design, we performed a meta-analysis combining results among all studies related to NINJ2 gene and ischemic stroke stratified by incident/first-ever ischemic stroke and prevalent stroke." (PMID 22212150, 2012). "Considering the previous significant association between rs34166160 and stroke, our study demonstrated that rs34166160 in the NINJ2 gene may be a shared genetic risk factor for CAD and stroke." (PMID 34897030, 2021). "In an analogous manner, NINJ2 might be a candidate gene for stroke prognosis since it may influence the reaction to brain cells to injury." (PMID 22212150, 2012). "Moreover, we studied if the NINJ2 genotypes affected post-stroke functional outcome at 1 year." (PMID 22429733, 2012). "So far, no studies have shown an association between the NINJ2 gene with stroke." (PMID 23554703, 2011). "Notably, the association with NINJ2 reported in CHARGE could also not be replicated in a recent very large meta-analysis by the International Stroke Genetics Consortium and Wellcome Trust Case-Control Consortium 2 (2010)." (PMID 22384361, 2011). "Previous studies, such as those examining NINJ2 or APOE polymorphisms, have linked specific alleles with earlier or later stroke presentation—even in the absence of traditional vascular risk factors." (PMID 41324337, 2026). "Until now, the impact of the NINJ2 SNP on stroke-related lesions on multi-sequence MR images has not been studied." (PMID 22429733, 2012). "When further investigating the NINJ2 associations by TOAST subtypes, none of the SNPs was significantly associated with any of the stroke subtype, either (data not shown)." (PMID 22384361, 2011).
ischemic stroke (10 papers, 2012 to 2025). A stroke disorder caused by obstruction of blood flow to the brain, due to thrombotic (local blood clot formation) or embolic (due to a blood clot or other material traveling from another site) event. "NINJ2 is typically expressed in mature sensory and enteric neurons and is associated with an increased risk of ischemic stroke." (PMID 40518514, 2025). "Under pathological conditions, NINJ2 is expressed in Schwann cells of injured nerves and is associated with an increased risk of ischemic stroke." (PMID 40518514, 2025). "We sequenced 196 kb around NINJ2 on chromosome 12p13 among 3,986 European ancestry participants, including 475 ischemic stroke cases, from the Atherosclerosis Risk in Communities Study, Cardiovascular Health Study, and Framingham Heart Study." (PMID 24959832, 2014). "Subsequent reports have been conflicting about the association of the NINJ2 SNPs with ischemic stroke." (PMID 24959832, 2014). "Only one novel intronic NINJ2 variant, rs34166160, showed an independent association with incident ischemic stroke." (PMID 24959832, 2014). "The GWAS finding and a large Japanese case control study presents an association between NINJ2 SNPs and ischemic stroke." (PMID 22212150, 2012). "In the present study, we tried to see if the NINJ2 SNP (A allele) would be associated with earlier-onset (vs. late-onset) first-ever ischemic stroke." (PMID 22429733, 2012). "Previous studies have found that NINJ2 is associated with nerve injury in ischemic stroke." (PMID 29069724, 2017). "Possible differences in the strength of association between NINJ2 variation and specific ischemic stroke etiologies may further erode our power to detect true effects." (PMID 24959832, 2014). "We previously conducted a genome-wide association study (GWAS) in four prospective studies from the Cohorts for Heart and Aging Research in Genomic Epidemiology (CHARGE) consortium and demonstrated that sequence variants near the NINJ2 gene are associated with incident ischemic stroke." (PMID 24959832, 2014). "Aggregating 278 putatively-functional variants with MAF≤ 1% using count statistics, we observed a nominally statistically significant association, with the burden of rare NINJ2 variants contributing to decreased ischemic stroke incidence (HR = 0.81; p = 0.026)." (PMID 24959832, 2014). "Here, we tested the hypothesis that the association between rs34166160 in NINJ2 and CAD, which is a low-frequency variant associated with ischemic stroke in Caucasians." (PMID 34897030, 2021). "In conclusion, resequencing of a 196-kb region around the NINJ2 gene in 3,986 European-American participants of 3 prospective cohorts of the CHARGE consortium identified novel associations of both common and rare variants with incident ischemic stroke." (PMID 24959832, 2014). "In order to clarify the role of sequence variation in this region in the etiology of incident ischemic stroke, we sequenced a 196 kb region of chromosome 12 that contains the NINJ2 gene, part of the WNK1 gene, and their intergenic sequence, among a subsample from 3 cohorts of the CHARGE consortium." (PMID 24959832, 2014). "We sequenced a 196-kb region around the NINJ2 gene in 3,986 participants from the CHARGE consortium and demonstrated evidence of association between newly-characterized, low frequency and rare sequence variants and ischemic stroke." (PMID 24959832, 2014). "For example, rs11833579 of WNK and rs12425791 of NINJ2 have been found closely associated with Asian stroke and ischemic stroke, respectively, and ARHGEF10 gene polymorphism is closely associated with the risk of ischemic stroke in Northern Han Chinese population." (PMID 29631604, 2018). "Our study found the initial NIHSS and mRS was not correlated with NINJ2 gene based upon genotype (data not shown), but further observed that first-ever ischemic stroke patients with the variant allele at these two SNPs had an increased risk of unfavorable outcome." (PMID 22212150, 2012).
colorectal cancer (8 papers, 2019 to 2025). A primary or metastatic malignant neoplasm that affects the colon or rectum. "Although previous studies have demonstrated that NINJ2 is upregulated in gliomas and colorectal cancer, the underlying mechanisms remain poorly understood." (PMID 40518514, 2025). "For instance, enhanced NINJ2 expression was reported to be associated with enhanced growth, survival and proliferation of human glioma and colorectal cancer cells." (PMID 33674652, 2021). "Moreover, both CUL2 and SOX6 are associated with colitis as well, while SERPINB9 and NINJ2 have been associated with colorectal cancer." (PMID 35371111, 2022). "NINJ2 expression is significantly upregulated in both glioma and human colorectal cancer, promoting cell growth via activation of the Akt and ERK signaling pathways." (PMID 40518514, 2025). "The NINJ2 gene codes Ninjurin 2 protein, and its overexpression promotes human colorectal cancer cell growth in vitro and in vivo." (PMID 38929750, 2024). "NINJ2 was observed to be overexpressed in colorectal cancer cells and can promote human colorectal cancer cell growth." (PMID 36910850, 2023). "Ninj2 was previously reported to contribute to neurite outgrowth and enhance growth, survival and proliferation of glioma and colorectal cancer cells." (PMID 33674652, 2021). "Some reports have suggested that NINJ2 could work as an oncogenic protein and the overexpression promotes cell growth in glioma and colorectal cancer cells." (PMID 35841085, 2022).
glioma (7 papers, 2019 to 2026). A benign or malignant brain and spinal cord tumor that arises from glial cells (astrocytes, oligodendrocytes, ependymal cells). "Contrarily, forced overexpression of Ninj2 by a lentiviral construct efficiently promoted glioma cell progression in vitro." (PMID 31794427, 2019). "In the glioma cells Akt and Erk activation was largely inhibited by Ninj2 shRNA/KO, but augmented with ectopic Ninj2 overexpression." (PMID 31794427, 2019). "In U251MG cells and the primary human glioma cells (“P1/P2”), “Transwell” and “Matrigel Transwell” assay results show that Ninj2 shRNA significantly decreased the number of migrated and invasive glioma cells." (PMID 31794427, 2019). "The results of present study demonstrated that in glioma cells Ninj2 co-immunoprecipitated with multiple RTKs (including EGFR, PDGFRβ and FGFR), required for downstream Akt and Erk activation." (PMID 31794427, 2019). "In the human glioma tissues (“T1/T2/T3”, derived three primary glioma patients), Ninj2-immunoprecipitation with EGFR, PDGFRβ and FGFR was detected as well." (PMID 31794427, 2019). "Collectively, these results show that Ninj2 overexpression promoted glioma cell progression in vitro." (PMID 31794427, 2019). "In established and primary human glioma cells, Ninj2 shRNA or knockout (by CRISPR/Cas9 gene editing) potently inhibited cell survival, growth, proliferation, cell migration and invasion, while inducing apoptosis activation." (PMID 31794427, 2019). "In U251MG cells and the primary human glioma cells (“P1/P2”), Ninj2 shRNA induced significant apoptosis activation, evidenced by increases of caspase-3 activity and TUNEL-positive nuclei ratio." (PMID 31794427, 2019). "Our results suggest that fully activation of the oncogenic RTKs (EGFR, PDGFR and FGFR) signaling requires Ninj2 in glioma cells." (PMID 31794427, 2019). "We show that Ninj2 mRNA and protein levels are significantly upregulated in human glioma cells and tissues." (PMID 31794427, 2019). "Ninj2 protein upregulation was detected as well in human glioma tissues (“T”), whereas its levels are relatively low in the paired surrounding normal brain tissues (“N”)." (PMID 31794427, 2019). "In U251MG cells and primary human glioma cells (“P1/P2”), Ninj2 shRNA similarly decreased EdU incorporation, suggesting proliferation inhibition." (PMID 31794427, 2019). "In U251MG cells and the primary human glioma cells (“P1/P2”), transfection of Ninj2 shRNA (“Seq1”) lentivirus resulted in significant viability (MTT OD) reduction and cell death (LDH release)." (PMID 31794427, 2019). "Akt and Erk activation was potently inhibited by Ninj2 shRNA or knockout, but enhanced with ectopic Ninj2 overexpression in glioma cells." (PMID 31794427, 2019). "In human glioma tissues and cells, Ninj2 co-immunoprecipitated with multiple receptor tyrosine kinases (EGFR, PDGFRβ and FGFR), required for downstream Akt and Erk activation." (PMID 31794427, 2019). "In the current study, we show that expression of Ninj2 is significantly increased in human glioma tissues, as compared to its levels in the surrounding normal brain tissues." (PMID 31794427, 2019). "Targeting the Ninj2-RTK signaling will be a potential valuable novel strategy to inhibit glioma cells." (PMID 31794427, 2019). "In established and primary human glioma cells, Ninj2 silencing (by targeted shRNAs) or knockout (by CRISPR/Cas9 method) potently inhibited cell survival, proliferation, migration and invasion, while inducing significant apoptosis activation." (PMID 31794427, 2019). "Future studies are certainly needed to further explore the significance of Ninj2 upregulation in the diagnosis and therapeutic of human glioma." (PMID 31794427, 2019). "In summary, we show that Ninj2 overexpression promotes glioma cell growth." (PMID 31794427, 2019). "Together, these results show that Ninj2 shRNA or KO inhibited glioma cell survival." (PMID 31794427, 2019).
glioma (continued). "Taken together, Ninj2 shRNA or KO inhibited human glioma cell migration and invasion in vitro." (PMID 31794427, 2019). "Contrarily, ectopic overexpression of Ninj2 promoted glioma cell progression in vitro." (PMID 31794427, 2019). "In the glioma tissues Ninj2 mRNA upregulation was also detected." (PMID 31794427, 2019). "Additionally, EdU-positive staining in A172 glioma cells was largely decreased after Ninj2 silencing or KO." (PMID 31794427, 2019). "Ninj2 protein levels were upregulated as well in glioma cells." (PMID 31794427, 2019). "Collectively, we show that Ninj2 overexpression promotes glioma cell progression, indicating that it could be a novel and valuable therapeutic target for human glioma." (PMID 31794427, 2019). "The results of the present study indicate that Ninj2 could be a novel oncogenic protein for human glioma." (PMID 31794427, 2019). "Here our results will show that overexpression of Ninj2 promotes human glioma cell progression." (PMID 31794427, 2019). "We therefore tested whether Ninj2 was important for glioma cell migration and invasion." (PMID 31794427, 2019). "By employing a co-immunoprecipitation (“Co-IP”) assay, we show that Ninj2 immunoprecipitated with EGFR, PDGFRβ and FGFR in A172 cells and primary human glioma cells (“P1/P2”)." (PMID 31794427, 2019). "As compared to the primary human astrocytes (from Dr. Cao at Soochow University), Ninj2 mRNA levels were significantly elevated in established human glioma cell lines (A172 and U251MG) and primary human glioma cells (derived from two human patients, “P1/P2”)." (PMID 31794427, 2019). "Similarly, CRISPR/Cas9-mediated knockout of Ninj2, a modulator of multiple RTKs including FGFR, demonstrated suppression of glioma cell survival and invasiveness, reinforcing broader intersection between RTK signaling and FGFR pathway regulation." (PMID 41584352, 2026). "“INPUT” results confirmed Ninj2, EGFR, PDGFRβ and FGFR expression in the glioma tissues." (PMID 31794427, 2019). "“INPUT” results confirmed Ninj2, EGFR, PDGFRβ and FGFR expression in the glioma cells." (PMID 31794427, 2019). "The expression and potential functions of Ninj2 in human glioma have not been extensively studied." (PMID 31794427, 2019).
Alzheimer disease (5 papers, 2011 to 2025). A progressive, neurodegenerative disease characterized by loss of function and death of nerve cells in several areas of the brain leading to loss of cognitive function such as memory and language. "It is interesting to note that genetic variants of NINJ2 have been associated with a decreased risk of Alzheimer’s disease." (PMID 24367640, 2013). "Recently, Ninj2 was reported to be a vascular susceptibility gene and associated with Alzheimer's disease risk." (PMID 23304210, 2012). "In conclusion, our study demonstrates that SLAMF8 and NINJ2 are key drivers of neuroinflammation and oxidative stress in Alzheimer’s disease by activating the TLR4/NF-κB pathway." (PMID 40394132, 2025). "This study aimed to investigate the expression and role of Signaling Lymphocytic Activation Molecule Family Member 8 (SLAMF8) in Alzheimer’s disease (AD), particularly its interaction with NINJ2 in the TLR4/NF-κB signaling pathway." (PMID 40394132, 2025). "It is interestingly to note that three (APBA2, APBA3 and NINJ2) of these genes are correlated with Alzheimer’s disease." (PMID 24367640, 2013).
atherosclerosis (3 papers, 2021 to 2025). A disease characterized by the build-up of fatty material and calcium deposition in the arterial wall resulting in partial or complete occlusion of the arterial lumen. "NINJ2 encodes the cell adhesion molecule, nerve injury-inducible protein 2 (Ninjurin2), which modulates vascular endothelial cell activation and inflammatory responses, affecting atherosclerosis and coronary artery disease." (PMID 40761743, 2025). "The expression of NINJ2 can be detected in cells directly involved in the inflammatory process of atherosclerosis, including vascular endothelial cells, monocytes, and macrophages." (PMID 34897030, 2021).